CHEK1 (checkpoint kinase 1)
Diseases named in the same sentence as CHEK1 in open-access papers (continued):
Sharing a sentence is not in itself a finding about the gene and the disease.
cancer (continued). "To determine if the interaction between CHEK1/2 and RAD17 was also present across a diverse set of cancer cell lines we analyzed data generated from Project Achilles, a cancer cell-line based functional genomic screen in which over 11,000 genes were knocked down with shRNA in 102 cell lines." (PMID 26437225, 2015). "While combined inhibitions generally showed synergistic effects, a study showed limited increase in cancer cell death with MK8776, reporting that CHEK1 depletion with siRNA or inhibition with MK-8776 only minimally sensitized Ovcar8 cells to TPT in colony formation assays." (PMID 25884494, 2015). "Other molecules up-regulated with a well-known function in cancer progression, are CDC2, a protein kinase that has a crucial role in cell cycle control and in cell cycle progression and CHEK1, a checkpoint kinase involved in DNA damage response, whose depletion leads to metaphase block." (PMID 19753302, 2009). "Thus, the cell-type-specific genetic pathways regulating the cell-type-specific function of CHEK1 and 2 for normal growth are unclear, especially in the absence of external DNA damage and in fully transformed cancer cell lines." (PMID 35110534, 2022). "In this study, the CHEK1 gene was overexpressed in four different cancers versus normal tissues." (PMID 32178478, 2020). "Furthermore, CHEK1, BUB1B, and MCM2 could promote cancer cell proliferation, and which were enriched in cell cycle pathways in GSEA analysis for CCA." (PMID 33221765, 2020). "Moreover, CHEK1 can directly phosphorylate CDC25A, thereby regulating the cell cycle and DNA damage response, indicating a potential role of DGUOK-AS1 in tumorigenesis and cancer progression." (PMID 32766141, 2020). "Similarly, inhibition of downstream DDR kinases, such as checkpoint kinase 1 (CHK1), potentiated the anti-cancer activities of chemotherapeutic agents, thereby illustrating that targeting of deregulated DDR proteins might be an effective strategy to reverse cancer drug resistance." (PMID 41154409, 2025). "However, at present, no CHEK1 inhibitors have been approved in Phase 3 clinical trials, due in part to cumulative normal tissue toxicities, off-target effects of simultaneous CHEK2 inhibition, and inefficient drug delivery in cancer patients." (PMID 34090465, 2021). "In addition, we identified that CHEK1 activated NEK2 (data not shown), an established MM CIN marker reported in our previous study, while NEK2 stimulated CIN in cancer cells by regulating CEP250, a core centrosomal protein essential for centriole–centriole cohesion." (PMID 34090465, 2021).
tumor (624 papers, 2007 to 2026). "Each of the four genes (HJURP, CDK1, FOXM1, and CHEK1) identified in the model has been implicated in cell cycle regulation and tumor development." (PMID 40299539, 2025). "Co-targeting MYC and CHEK1 activities synergistically inhibits CTDNEP1-deficient MYC-amplified tumor growth and prolongs animal survival." (PMID 36765089, 2023). "CHEK1 is also associated with an aggressive tumor phenotype and epithelial-mesenchymal transition (EMT)." (PMID 35428780, 2022). "The overexpression of CHEK1 was postulated to lead to tumor development and a risk factor in prognostics." (PMID 33662042, 2021). "It has been suggested that this is probably due to a deficiency in HRR associated genes ATM, MRE11A, H2AFX, and CHEK1; such tumours very rarely have concurrent MYCN amplification." (PMID 32577161, 2020). "Upon combined treatment, for two substrates, NUMA1 S395 and CHEK1 S345, the gain and loss of phosphorylation, respectively, were recapitulated using invivo tumor models by immunohistochemistry, with possible utility in future translational research." (PMID 32336009, 2020). "These analyses encompass cell cycle genes (e.g., AURKA and CHEK1) that have been shown to be preferentially actionable against RB1 deficient tumor models." (PMID 32242058, 2020). "Intriguingly, CHEK1 knockdown caused tumor-specific cell death of HNSCC cells in comparison to primary cells." (PMID 31209198, 2019). "In general, elevated expression of CDC6 mRNA was associated with increased CHEK1 mRNA expression in the tumour samples compared to normal tissue from the same site." (PMID 27775084, 2016). "The risk allele of rs2059614 was associated with increased expression of EI24 and CHEK1 in normal breast epithelium adjacent to tumor from the METABRIC study (P = .002 and .007, respectively) (available online)." (PMID 25890600, 2015). "We also found that high levels of CHEK1 protein in tumor tissues were associated with poor NSCLC survival." (PMID 25840419, 2015). "To assess if CHEK1 expression in NSCLC was associated with patient survival, we measured CHEK1 expression in 276 tumor samples with immunohistochemical staining (IHC)." (PMID 25840419, 2015). "The borderline significant inverse association of KRAS mutation and high expression of Chek1 is well in line with the association of KRAS wild-type tumours being more genetically unstable." (PMID 23800114, 2013). "Clinically, higher tumor CHEK1 levels are associated with poorer response to anti-PD-1 therapy." (PMID 41722056, 2026). "Furthermore, CHEK1 expression is associated with tumor grade and disease recurrence, suggesting its significant role in tumorigenesis and progression." (PMID 41564103, 2026). "Notably, the platform successfully executed queries targeting rare subgroups, such as CHEK1-mutated CRC stratified by tumor stage, despite limited sample sizes." (PMID 40940961, 2025). "In step with these findings, the complete loss of CHEK1 suppresses chemically induced carcinogenesis, whereas tumor cells with increased levels of CHEK1 may acquire survival advantages due to the ability to resist chemotherapy-induced DNA damage." (PMID 39456660, 2024). "For the first time, an association between components of the KRAS/ATR/CHEK1-signaling pathway, responsible for coordinating replicative stress, and markers of tumor progression, including invasiveness and tumor recurrence, has been established in patients with stage I ECE." (PMID 38669256, 2024).
tumor (continued). "Checkpoint kinase 1 (Chk1) is an essential protein in G2 checkpoint activation, and the disruption of the ATR-Chk1 axis can force checkpoint deficient tumor cells to proceed through the cell cycle harboring lethal DNA damage caused by IR, with consequent activation of cell death programs." (PMID 34746010, 2021). "Studies have shown that complete loss of CHEK1 suppresses chemically induced carcinogenesis, and its low expression may result in tumor progression." (PMID 32178478, 2020). "Indeed, targeting members of DDR such as ATM (ataxia telangiectasia mutated) and CHK1 (checkpoint kinase 1), amplifies DNA damage and induces lethality on tumor cells." (PMID 31947935, 2020). "Single-cell transcriptomics reveals a CHEK1-high subpopulation exhibiting stem-like and immune-suppressed features, linking tumor-intrinsic fitness to microenvironment remodeling." (PMID 41722056, 2026). "Exemplified by CHEK1, these findings establish MIGs as dual therapeutic targets capable of simultaneously disrupting tumor-intrinsic fitness and remodeling the immunosuppressive niche." (PMID 41722056, 2026). "A synergistic combination of checkpoint kinase 1 inhibitor (CHK1i) with low-dose hydroxyurea (LDHU) promotes a unique ATR-independent moderate replication stress response with potent anti-tumour effects." (PMID 41946828, 2026). "Collectively, these studies consolidate the role of CHEK1 as a biomarker for tumor progression and adverse prognosis." (PMID 41564103, 2026). "Tumor cells exhibiting elevated levels of CHEK1 acquire a survival advantage by resisting increased DNA damage." (PMID 41564103, 2026). "Shiyu Zhang and colleagues found that Checkpoint kinase 1 (CHK1) is abnormally overexpressed in HCC and is associated with tumor progression and poor prognosis." (PMID 40386780, 2025). "Mechanistically, selinexor reduces Myc binding to the RAD51 and CHEK1 promoters, thereby decreasing the expression of DNA repair proteins and sensitizing tumor cells to platinum-induced DNA damage." (PMID 41440011, 2025). "Therapeutic targeting of irradiation-induced autophagy, particularly through pharmacological blockade of checkpoint kinase 1 (Chk1), disrupts cytoprotective autophagy, exacerbating radiation-induced DNA damage and enhancing tumor cell killing." (PMID 41009794, 2025). "Through Western blot experiments, we foundthat increased RRM2 expression significantly elevated the expressionof cell cycle- and DNA damage repair-related proteins, such as cyclinB1 and CHEK1, in both tumor cells and HVECs." (PMID 40834268, 2025). "In Luminal subtypes, overexpression of CHEK1 promotes tumor cell survival by inhibiting replication stress-induced apoptosis." (PMID 40344565, 2025). "Further bioinformatics analysis of miR-24-1-5p targets, including CD34, ACACA, TPM3, UFC1, EDIL3, and CHEK1, reinforces their role in tumor immune cell infiltration and the transformation of the tumor microenvironment." (PMID 38840234, 2024). "Initially, CHEK1 was thought to be a tumor suppressor because of the role it plays in the DNA damage response and cell cycle checkpoint response." (PMID 39456660, 2024). "Immunohistochemistry analysis revealed higher protein expression of these hub MCGs in tumor tissue (except for CHEK1) via the HPA website." (PMID 39015573, 2024). "To examine the effect of inhibition of MYC and CHEK1 on the growth of human G3 MB tumor cells, we treated MYC-driven D425 MB cells with JQ1 or prexasertib individually or in combination." (PMID 36765089, 2023). "These putative positive correlations show that a high CDK1/PBK/CHEK1 expression promotes tumor growth, aggressiveness, and immune evasion through the increased recruitment of T Cells CD4+ Th2, MDSCs, and TAM-M2, all of which have pro-tumor effects." (PMID 38003585, 2023).
tumor (continued). "Studies have shown that the selective inhibition of CDK1, PBK, and CHEK1 arrests tumor progression in sarcomas, GBM, prostate, endometrial, and breast cancers by blocking the G2-M phase transition and promoting apoptosis." (PMID 38003585, 2023). "Our findings indicate that HMJ-38 targets BRD4, CDK2, CHEK1/2, and EGFR, which have been implicated in the death of tumor cells and DNA damage pathways." (PMID 38532833, 2023). "Our previous study showed that tumor cells treated with 2 mM HU for 18 h resulted in one-end DNA double-strand breaks, activated the checkpoint kinase-1 (Chk1) signaling pathway and arrested tumor cells in the S phase." (PMID 36781846, 2023). "The expression of CHEK1 was related to tumor size, lymph node metastasis and tumor stage (P < 0.05), but independent from gender and age of patients (P > 0.05)." (PMID 35428780, 2022). "Prexasertib is an inhibitor of Checkpoint Kinase 1 (CHEK1) that was recently shown to be effective in pediatric tumor PDX models, including DSRCT." (PMID 35443736, 2022). "CDK1, AURKB, CCNA2, and CHEK1 were highly expressed in immune cells, suggesting that histone phosphorylation is closely related to the tumor immune environment." (PMID 36120466, 2022). "By contrast, targeting CHEK1 by shRNA KD significantly inhibited MM tumor growth relative to WT controls." (PMID 34090465, 2021). "Conversely, targeting CHEK1 by doxycycline-inducible h-CHEK1 shRNA significantly inhibited tumor growth when NOD-SCID mice were administered doxycycline through drinking water to induce h-CHEK1 shRNA expression." (PMID 34090465, 2021). "Paired pre- and post-treatment blood and fat pad biopsies to assess histone acetylation, as well as paired tumor biopsies to evaluate checkpoint kinase 1 (CHK1) expression as a pharmacodynamic biomarker, were obtained." (PMID 34680389, 2021). "CHEK1 overexpression in MM cells not only promoted tumor growth, but also conferred partial resistance to the chemotherapeutic drugs BTZ and ADR." (PMID 34090465, 2021). "After 28 days, we visually observed that tumors derived from CHEK1-OE cells grew faster than tumors derived from WT cells, with significantly increased tumor volume and weight." (PMID 34090465, 2021). "The correlation of CHEK1 expression with tumor grade and disease recurrence was also reported, suggesting its role in tumor development." (PMID 32178478, 2020). "Tumor cells with increased levels of CHEK1 acquire survival advantages due to the ability to resist a higher level of DNA damage." (PMID 32178478, 2020). "Further, mRNA E2F3 and CHEK1 were upregulated in the tumor group, which conformed to the ceRNA theory." (PMID 33232580, 2020). "The CHEK1 gene was previously thought to function as a tumor suppressor because of the regulatory role it plays in DNA damage." (PMID 32178478, 2020). "Consistent with the GSEA data, KRAS was preferentially expressed in the edge tumor cells and both c-Myc and CHEK1 were present in the core regions, To further validate these results, we developed another model by using slice cultures of neonatal mouse brains." (PMID 32938908, 2020). "In GSE45436, SNHG11, CRNDE, MYLK‐AS1, E2F3, and CHEK1 were highly expressed in the tumor group, while RASGEF1B was the opposite, which were consistent with the results of TCGA." (PMID 33232580, 2020). "It is also a known BC susceptibility gene shown to phosphorylate several tumour suppressors such as BRCA1, CHEK1 and TP5350,51." (PMID 32632202, 2020). "Among the genes related to prognosis, the expression levels of CCNB1, NQO1, NUF2, and CHEK1 were high in tumor tissues (p < 0.05)." (PMID 33424998, 2020). "CHEK1 overexpression was correlated with advanced tumor stages, proximal tumor localization, and worse prognosis." (PMID 32153633, 2020).
tumor (continued). "AZD7762 is a checkpoint kinase 1 (Chk 1) inhibitor, which has been reported to sensitize many tumor cells to DNA damage." (PMID 31372095, 2019). "CHEK1 (checkpoint kinase 1), a conserved serine/threonine kinase, plays a key role in tumor growth promotion." (PMID 30886771, 2019). "c-Myc also increases resistance of tumor cells to irradiation by regulating downstream genes such as cyclin-dependent kinase 4 (CDK4), ataxia-telangiectasia mutated kinase (ATM), checkpoint kinase 1 (Chk1), and Chk2." (PMID 29871674, 2018). "The boxplots showed that the expression levels of CCNB1, CCNB2, and CHEK1 were significantly higher in primary tumor than those in the normal liver for LIHC patients from TCGA (p<0.001)." (PMID 30228980, 2018). "Fold changes in CDC6 or CHEK1 mRNA expression in human tumours compared to normal tissue controls were determined using the Firehose analysis tool from the Broad Institute TCGA Genome Data Analysis Center." (PMID 27775084, 2016). "Our bioinformatic analysis and cell culture experiments further indicate that the tumor suppressing effects of miR-195 were mediated in part through its down-regulation of CHEK1 mRNA, a cell cycle modulator." (PMID 25840419, 2015). "Collectively, high miR-195 and low CHEK1 work synergistically suppressing tumor growth and improving the survival outcome of NSCLC patients." (PMID 25840419, 2015). "Our analysis showed down-regulation of miR-195 and up-regulation of CHEK1 in tumor samples in comparison to adjacent tissues." (PMID 25840419, 2015). "Mechanistically, CHEK1 may promote tumor growth by modulating transcription factors like Myc to influence the expression of genes involved in cell proliferation." (PMID 41564103, 2026). "Telomere attrition can elicit a persistent DNA damage response, thereby activating the ATM/ATR-checkpoint kinase 1 (CHK1) pathway and facilitating immune surveillance evasion by upregulating PD-L1 expression, ultimately promoting tumor cell immune tolerance and progression." (PMID 40510156, 2025). "To assess whether the pathomic model of CHEK1 expression could guide patient immunotherapy, we analyzed the correlation between tumor mutational burden (TMB) and CHEK1 expression levels." (PMID 40344565, 2025). "In contrast, CHEK1 and PLK1 are cell cycle regulators, whose high expression is associated with enhanced tumor cell proliferation, offering a molecular explanation for the poorer prognosis and potentially reduced responsiveness to conventional immunotherapies in the high-risk group." (PMID 41278297, 2025). "While CCNB1 and CHEK1 showed decreased eigenvector centrality in metastasis, CHEK1 plays a key role in the DNA damage response and contributes to tumor progression and therapy resistance in PCa, particularly in metastatic castration-resistant prostate cancer (CRPC)." (PMID 40626556, 2025). "The key gene “CHEK1” expression was statistically different between tumor and normal groups." (PMID 38358910, 2024). "To elucidate the differences in KRAS, ATR, CHEK1 mRNA expression levels between the two analyzed group of samples, we checked for their correlation with tumor grade differentiation and depth of myometrium invasion, which are key clinicopathological indicators of tumor progression." (PMID 38669256, 2024). "Moreover, the presence of CHEK1 correlates with the severity and reappearance of tumors, suggesting its role in tumor progression." (PMID 38633613, 2024). "Moreover, the CHEK1 gene was overexpressed in several solid tumors, and its expression was correlated with the tumor grade and disease recurrence." (PMID 39456660, 2024).